TNFRSF4 (TNF receptor superfamily member 4)
Diseases named in the same sentence as TNFRSF4 in open-access papers (continued):
Sharing a sentence is not in itself a finding about the gene and the disease.
tumor (continued). "Also important are TNFRSF17, TNFRSF18, TNFRSF4, members of the Tumor Necrosis Factor Receptor superfamily that bind to various TRAF family members and can regulate tumor cell proliferation and death." (PMID 39888956, 2025). "In vivo, localized ablation selectively suppressed tumor growth without systemic toxicity, increasing TNFRSF4+ while decreasing CTLA-4+ Treg subsets." (PMID 41208977, 2025). "Targeting TNFRSF4 and CTLA-4 pathways could arouse effective T cells to drive a robust anti-tumor response." (PMID 40535819, 2025). "Moreover, the expression of ADAM10 was reciprocally exclusive with some tumor immune checkpoint genes, such as VEGFB, LAG3, IL4, TNFRSF18, TNFRSF4, TNF receptor superfamily member 14 (TNFRSF14), CD27, CCL5, etc.." (PMID 39211038, 2024). "Encouragingly, recent evidence demonstrated that TNFRSF4 plays a key role in stabilizing TEM in UCEC, suggesting that TNFRSF4 may be a promising therapeutic target for T cell-mediated anti-tumor immunotherapy in UCEC patients." (PMID 36253800, 2022). "Among them, CTLA4, TIGIT, TNFRSF4 and TNFRSF18 were highly expressed in tumor-infiltrating Tregs." (PMID 35562760, 2022). "The results showed that m6Ascore was negatively correlated with the expression of TMIGD2, TNFRSF18, TNFRSF25, TNFRSF4, TNFRSF8, and NRP1, indicating that the poor prognosis of high-m6Ascore patients might be due to the tumor immunosuppressive microenvironment." (PMID 36313417, 2022). "Our investigation found that transcriptome signatures of immune-related activities were positively correlated with TNFRSF4 and chiefly enriched in inflammatory signaling pathways, such as IFN-γ response, which is essential for CD8+ T lymphocyte-mediated anti-tumor immunity." (PMID 35562682, 2022). "OX40 (CD134/TNFRSF4), a costimulatory receptor of the TNF receptor superfamily ((TNFRSF), has emerged as a compelling immuno-oncology target given its capacity to amplify T-cell activation, sustain effector and memory responses, and remodel the tumor microenvironment (TME)." (PMID 41737211, 2026). "Importantly, differential TNFRSF4 expression was identified in tumour cells rather than lymphocytes." (PMID 38809883, 2024). "Indeed, CD8+ T cells in the tumor periphery showed increased expression of genes belonging to costimulatory pathways, including ICOS, TNFRSF4 (OX40) and TNFRSF9 (4-1BB), albeit accompanied by high levels of inhibitory receptors PDCD1 (PD-1), LAG3, HAVCR2 (TIM-3), and CTLA4." (PMID 38127790, 2023). "Moreover, mIHC staining confirmed different expression levels of CD68+ &APOE+ macrophages, FOXP3+ &TNFRSF4+ Tregs, VEGFA, and TGFβ signaling between the tumor microenvironment of the de novo mild OLK and the OLK with moderate to severe dysplasia in clinical study." (PMID 36914617, 2023). "TNFRSF4 (also known as CD134/OX40) is one of the representative targets of second-generation immune checkpoints, and its clinical efficacy has been observed by anti-TNFRSF4 (MEDI6469) therapy in HNSCC patients through regulating antigen-specific tumor-infiltrating T cells." (PMID 34220923, 2021). "For example, OX40 (CD134/TNFRSF4) is such a cell surface-expressed marker of T-cell activation and it has been used to image the spatiotemporal dynamics of T-cell activation following in situ vaccination with CpG oligodeoxynucleotide in a dual tumor-bearing mouse model." (PMID 32327996, 2020). "In vivo, localized MWA selectively suppressed tumor growth without systemic toxicity, coinciding with a reduction in CTLA-4+ Treg subsets and an increase in TNFRSF4+ Tregs." (PMID 41208977, 2025). "We found that besides TNFRSF4, Treg functional signature genes such as FoxP3, CTLA4, TIGIT, TNFRSF18 (GIRT), CCR8, LAYN, and MAGEH1 were also overexpressed in C11-Tregs-FoxP3 of treatment-naive and non-MPR tumor lesions, but not for MPR tumor lesions." (PMID 35831283, 2022).
cancer (268 papers, 2012 to 2026). A tumor composed of atypical neoplastic, often pleomorphic cells that invade other tissues. "Increased expression of TNFRSF19 has been linked to poor prognosis in some cancers, whereas TNFRSF4 (OX40) enhances CD8 T cell infiltration." (PMID 39857718, 2025). "TNFRSF4, also known as OX40, is used as a target of immunotherapy for various cancers, including HNSCC, and is associated with a good prognosis." (PMID 35935989, 2022). "Subsequent analysis also demonstrated a clear relationship between GPX4 expression and key immune checkpoints such as VEGFB, TGFB1, CD276, TNFRSF18, and TNFRSF4 across most cancer types." (PMID 41142608, 2025). "The prognostic power of TNFRSF4 has already been studied in several cancers, with some contrasting results." (PMID 38809883, 2024). "Specifically, several immune checkpoints including TNFRSF18, TNFRSF4, VSIR, LGALS9, HAVCR2, and TNFRSF14 are significantly associated with RARA-AS1 in more than 10 types of cancer." (PMID 37833349, 2023). "The expression profiles of cancer-related checkpoints showed that the majority of checkpoint-target genes had low expression levels in the high-risk group, and only TNFRSF25, TNFRSF4, TNFRSF14, TNFRSF18, and CD276 were upregulated in the high-risk group." (PMID 37190215, 2023). "Encouragingly, the latest evidence reinforced the notion that immunotherapy with TNFRSF4 agonists would trigger a new trend in cancer therapies." (PMID 35562682, 2022). "Previous studies have shown that, among these genes, CTLA4, IGF2BP2, and TNFRSF4 are involved in cancer procession and affect the prognosis of patients with OSCC." (PMID 36185403, 2022). "Several anti-TNFRSF4 agonistic monoclonal antibodies are currently being tested in early-phase cancer clinical trials." (PMID 34133324, 2021). "This study demonstrates that MWA disrupts Treg immunosuppression, likely by activating OX40L/TNFRSF4 signaling, and favorably alters the balance of effector to suppressor cells, providing a novel rationale for combining thermal ablation with OX40-targeted immunotherapies in cancer treatment." (PMID 41208977, 2025). "TNFRSF4, barely reported on EC but was a high-profile target on other cancers." (PMID 35562682, 2022). "Recently, TNFRSF4 (OX40) has emerged as a potential target for cancer immunotherapy." (PMID 36323801, 2022). "TNFRSF4 and TNFSF4 mutations in cancers were rarely reported." (PMID 34900670, 2021). "TNFRSF4 possesses potential as a target upon cancer immunotherapy." (PMID 35071320, 2021). "They markedly expressed co-stimulatory molecules (e.g., TNFRSF4, TNFRSF9, TNFRSF18), adhesion, and IFN response signatures in the very late stage of cancer." (PMID 38645221, 2024). "In pan-cancer, HMGB1 had the highest positive correlation with NUDT21, followed by TLR4, CD276, and TNFRSF4." (PMID 38349866, 2024). "Mechanistically, LLNLR-299G3.1 bound to cancer-associated RNA binding proteins and regulated the expression of cancer-related genes, including OSM, TNFRSF4, HRH3, and SSTR3." (PMID 37415734, 2023). "It was also detected that HIC1 expression was positively related to several immunestimulators in different cancers, such as CXCL12 and TNFRSF4, and was negatively connected with IL-6R in TGCT." (PMID 37388742, 2023). "TNFRSF4 was first discovered on the surface of activated CD4+ T cells, which played a vital role in immune regulation in multiple cancers as a crucial immune checkpoint." (PMID 35562682, 2022). "CD276 showed the highest positive correlations with JMJD8 in 15 cancers, followed by LGALS9, VSIR, and TNFRSF4." (PMID 35898493, 2022). "On the other hand, the medium-expression group included TNFRSF18, TNFRSF4, CD27, and LAG3 and their expression levels varied significantly among the different cancer samples." (PMID 36157232, 2022).
cancer (continued). "Correlation analyses between YIF1B and checkpoint gene expression found a high correlation (P<0.05) with tumor necrosis factor (TNF)-related immune genes (TNFRSF4, 8, 14, 18) and CD276 (B7H3) in various cancer types." (PMID 32648580, 2020). "TNFRSF4 (OX40, CD134) and its binding partner are members of the TNFR/TNF superfamily and are involved in the control of inflammatory diseases and cancer." (PMID 30700253, 2019). "Furthermore, the expression of GPX4 was closely associated with MHC molecules, immune activation genes, and immunosuppressive genes such as HLA-A, HLA-B, CD160, TNFRSF18, TNFRSF4 and CD276 in most cancer types." (PMID 41142608, 2025). "Similarly, ZNF668 was positively correlated with PVRL2 (Nectin-2), CD276 (B7-H3), TGFB1, and multiple members of the TNF receptor superfamily, including TNFRSF4 (OX40), TNFRSF18 (GITR), and TNFRSF25, in the vast majority of analyzed cancers." (PMID 41614761, 2025). "T-cell co-stimulatory receptors that belong to the tumor necrosis factor receptor superfamily (TNFRSF), including OX40 receptor (CD134; TNFRSF4), 4-1BB (CD137; TNFRSF9), and glucocorticoid-induced TNFR-related (GITR) protein (CD357; TNFRSF18), are potential targets for cancer immunotherapy." (PMID 38526805, 2024). "In diverse cancer types, the correlation between OAS3 and the expression of checkpoint genes indicated a high correlation with TNF-related immune genes including TNFRSF14, TNFRSF8, TNFRSF25, TNFRSF4, TNFRSF18, TNFSF15, and TNFRSF9." (PMID 35592250, 2022). "The tumor necrosis factor receptor superfamily, member 4 (TNFRSF4), also known as CD134 and OX40 receptor, is another member of the TNFR-superfamily of receptors that have gained interest as therapeutic target molecules for cancer immunotherapy." (PMID 33802281, 2021). "For example, CD28, CD40, and TNFRSF4 (OX40) antagonists are in early stage clinical trials for treatment of various immune disorders, whereas CD28, CD40, and TNFRSF4 (OX40) agonists are in early stage clinical trials for various cancer indications." (PMID 28822103, 2018). "The OX40, that is, “tumor necrosis factor receptor superfamily, member 4” (CD134, TNFRSF4) and its ligand OX40L,” “tumor necrosis factor (ligand) superfamily, member 4” (OX40L, CD252, TNFSF4), are fundamental in augmenting the immune response against cancer cells." (PMID 36652956, 2023). "However many other conventional immune checkpoints such as TIGIT, TNFRSF4 (OX40 receptor/CD134), TNFRSF9 (4-1BB/CD137), and TNFRSF18 (GITR) are not universally overexpressed in cytotoxic CD4+ T cells from cancer patients." (PMID 34910940, 2021).
infection (61 papers, 2008 to 2026). The state of being infected such as from the introduction of a foreign agent such as serum, vaccine, antigenic substance or organism. "Ccr7+Ido1+ DCs, Cd160+Cd8+ T cells, and Tnfrsf4+Cd4+ T cells all increased after infection, and were viral RNA-positive, suggesting direct involvement of these immunity hubs against SARS-CoV-2 infection." (PMID 39414763, 2024). "TNFSF4/5/10 and TNFRSF4/8/9/13B were influenced during DTMUV infection and all these factors function as important proinflammatory genes and play vital roles in the inflammatory response." (PMID 35585616, 2022). "TNFRSF4 (also known as OX40 or CD134) is a member of the tumor necrosis factor receptor superfamily, subserving co-stimulatory functions of T-cells during infection." (PMID 34133324, 2021).
blood cancers (3 papers, 2022 to 2024). "Among the proteins associated with risk of haematological cancers, we identified associations with risk of multiple blood cancers for members of the FC-receptor protein [FCRL1, FCRL2, FCRL3, FCRL5, FCRLB] and TNF receptor families [TNFRSF4, TNFRSF9, TNFRSF13B, TNFRSF13C, TNFSF13B, TNFSF13]." (PMID 38750076, 2024).
brain disorder (1 paper, 2025). A disease affecting the brain or part of the brain. "Of the significant reverse MR relationships, the brain disorders demonstrated associations with the increased expression of six proteins (PAMR1, MAVS, F11R, REN, GER and LEPR) and decreased expression of three proteins (TNFRSF4, BTN2A1, ENPP6)." (PMID 40456753, 2025).
TNFRSF4 also shares sentences with these, for which no sentence is quoted: atopic dermatitis (20 papers); viral infection (19); asthma (17); lymphoma (16); rheumatoid arthritis (14); B-cell lymphoma (11); allergic disease (10); head and neck squamous cell carcinoma (10); pancreatic cancer (10); gastric cancer (8); influenza (8); non-small cell lung carcinoma (8); acute myeloid leukemia (7); head and neck cancer (7); immune disorders (6); infectious disease (6); type 1 diabetes mellitus (6); Arthritis (5); breast tumor (5); multiple sclerosis (5); triple-negative breast carcinoma (5); tuberculosis (5); allergic asthma (4); bladder cancer (4); graft versus host disease (4); HIV-1 infection (4); Immunodeficiency (4); metastatic melanoma (4); prostate carcinoma (4); thymoma (4).
A further 170 diseases each share a sentence with TNFRSF4 in 4 papers or fewer.